TFDP3 (transcription factor Dp family member 3)
Diseases named in the same sentence as TFDP3 in open-access papers (continued):
Sharing a sentence is not in itself a finding about the gene and the disease.
cancer (10 papers, 2004 to 2021). A tumor composed of atypical neoplastic, often pleomorphic cells that invade other tissues. "This suggests that TFDP3 may increase the drug resistance of cancer cells and reduce the cell death caused by apoptosis." (PMID 30235236, 2018). "In addition, TFDP3 is a tumor-associated antigen only expressed in malignant tumor tissues and normal testicular tissue." (PMID 30235236, 2018). "During DNA damage response in cancer cells, TFDP3 is induced and can inhibit E2F1-mediated apoptosis." (PMID 34745961, 2021). "Since TFDP3 plays an important role in the onset and development of multiple cancer, it appears to be a promising therapeutic target for the discovery of new cancer treatments." (PMID 34745961, 2021). "As already reported, TFDP3 belongs to cancer-testis antigens which are mainly expressed in germinal and cancer cells; they can be found in some diseases as a prerequisite for downstream immune target-discovery projects." (PMID 34745961, 2021). "A better understanding of TFDP3 will provide new insights into the pathological mechanisms and therapeutic strategies for cancers." (PMID 34745961, 2021). "This review focuses on the characterization of TFDP3, the involvement of TFDP3 in basic cell life processes and cancer development, as well as the mechanism of TFDP3 in the regulation of E2F-induced activity." (PMID 34745961, 2021). "TFDP3 is expressed in most cancer tissues and potentially plays a role in cell differentiation and proliferation." (PMID 32587798, 2020). "TFDP3 is a cancer/testis antigen and, a member of the DP family of transcription factors which is encoded by a gene located on the long arm of chromosome X at position Xq26.2." (PMID 30235236, 2018). "The results of our study show that the cancer/testis antigen TFDP3 molecule is a potential tumor antigen marker; and, also, one of the important transcriptional regulatory molecules of chemotherapy drug resistance." (PMID 30235236, 2018). "The results show that, under the treatment of chemotherapy drugs, the drug resistance of cancer cells through autophagy activation is closely related to the expression level of TFDP3." (PMID 30235236, 2018). "This study provides an important experimental basis for reducing the autophagy-associated tumor cell resistance and improving the comprehensive therapeutic effect of cancers by regulating the expression and activity of TFDP3." (PMID 30235236, 2018). "This study confirmed that TFDP3 molecule is a cancer-testis antigen, and TFDP3 expresses in addition malignant tumor cell lines(such as HepG2), but also in the immortalized hepatocellular cell line(L-02)." (PMID 28797103, 2017). "On the other hand, as a cancer-testis antigen molecule with clear functions, TFDP3 is related to the occurrence and development of cancers and germ cell development." (PMID 28797103, 2017). "Collectively, TFDP3 confers chemoresistance in MRD within childhood T-ALL, indicating that TFDP3 is a potential gene therapy target for residual cancer." (PMID 27902457, 2017). "Previous studies have reported that TFDP3 is expressed in the testis and in multiple cancer tissues, including, but not limited to, the cerebrum, esophagus and skin, and that it is weakly expressed in the normal pancreas." (PMID 28114432, 2017). "On one hand, as a cancer-testis antigen, TFDP3 has good immunogenicity, and is expressed only in tumor cells and testicular spermatogenic cells (which not express HLA molecules), is a good specific CTL target." (PMID 28797103, 2017). "The domain of testicular antigens is a good target molecule for genetically engineered T cells in the treatment of tumors, for TFDP3 is a cancer-testis antigen." (PMID 28797103, 2017).
cancer (continued). "The two peptides of TFDP3 are hence attractive candidates for human cancer immunotherapy." (PMID 34745961, 2021). "It has been approved that TFDP3 can promote cancer occurrence by modulating the cell cycle." (PMID 34745961, 2021). "In the treatment of malignant tumors, the demethylation in the promoter region of TFDP3 could continuously upregulate the expression of TFDP3 in cancer cells." (PMID 30235236, 2018). "This study explored the function of TFDP3 in cancer cell autophagy combining with E2F1." (PMID 30235236, 2018). "Unfortunately, TFDP3 expression can trigger autophagy by upregulating the expression of autophagic key proteins and increasing the number of autophagosomes during chemotherapy of malignant tumors, therefore TFDP3 attributes chemical resistance by repairing damaged DNA of cancer cells." (PMID 34745961, 2021). "Thus, it is possible that TFDP3 is a potential gene therapy target for residual cancer." (PMID 34745961, 2021). "In addition, sets of genes controlled by TFDP3 are involved in processes that are well-known hallmarks of cancer, which inferred that using TFDP3 as a biomarker for cancer diagnosis could be feasible." (PMID 34745961, 2021). "However, in various cancer cells, the expression of TFDP3 molecule is much higher." (PMID 30235236, 2018). "Furthermore, TFDP3 target therapy may also work with immunotherapy as a part of combined treatment method for cancer." (PMID 30235236, 2018). "Had been transfected with TFDP3-siRNA, the TFDP3 expression rate in the MDA-MB-231 cancer cell dropped and the apoptosis rate increased beyond that of the control group." (PMID 30235236, 2018). "Downregulation of the expression of TFDP3 through the application of siRNA can inhibit the expression of the autophagy-related protein, LC3, and can reduce the number of autophagosomes in cancer cells." (PMID 30235236, 2018). "However, whether there is a correlation between TFDP3 and cancer stem cells remains unknown." (PMID 28114432, 2017). "Our results showed that TFDP3 expression can induce autophagy by up-regulating the expression of autophagic key protein LC3(MAP1LC3) and increasing the number of autophagosomes during chemotherapy of malignant tumors." (PMID 30235236, 2018). "Our results show that overexpression of TFDP3 can induce autophagy by up-regulating the expression of autophagy marker light chain 3(LC3, MAP1LC3) and increasing the number of autophagosomes during chemotherapy of malignant tumors." (PMID 30235236, 2018). "To date, no human cancer clinical trials have been conducted to target TFDP3." (PMID 34745961, 2021). "In addition, despite that TFDP3 was confirmed to be a potential therapeutic target in cancer, there are still no drugs targeting TFDP3 for cancer therapy." (PMID 34745961, 2021). "Collectively, these data illustrated that TFDP3 might be exclusively expressed in carcinomas since it was not expressed in inflammatory diseases or in the benign tissues of the breast." (PMID 28114432, 2017).
tumor (9 papers, 2012 to 2021). "In addition, TFDP3 has also been found to be a tumor-associated antigen that only expresses in malignant tumor tissue and normal testicular tissue; Thus, it is closely related to tumor occurrence and development." (PMID 30235236, 2018). "When siRNA inhibits TFDP3 expression, it can reduce cell autophagy, improving the sensitivity of tumor cells to chemotherapy drugs." (PMID 30235236, 2018). "With the deployment of siRNA interference technology in vitro, one can recover the sensitivity of chemotherapy drugs in drug-resistant tumor cells by downregulating the expression of TFDP3." (PMID 30235236, 2018). "The recent researches about TFDP3 mostly focused on its ability to control the drug resistance and apoptosis of tumor cells." (PMID 28797103, 2017). "By knocking down the TFDP3 expression level in L-02 and HepG2 cell lines, the cell cycle would be arrested in S phase, which confirmed that TFDP3 can be a potential target for tumor therapy." (PMID 28797103, 2017). "The tumor cells would then undergo normal cell proliferation once TFDP3 was degraded or cleaved by intrinsic pathways, and therefore, there would be a G1 to S phase arrest, but no interference on cell cycle progression." (PMID 28114432, 2017). "Moreover, the overexpression of TFDP3 in normal cells should be conducted, in order to discover the roles of TFDP3 in tumor development." (PMID 34745961, 2021). "Thus, the siRNAs targeting TFDP3, which makes it possible to reduce tumor drug resistance, can be used to prolong the patient’s survival." (PMID 34745961, 2021). "Moreover, our recent research had focused on the ability of TFDP3 to influence the drug resistance and apoptosis of tumor cells." (PMID 30235236, 2018). "Our former research demonstrated that TFDP3 is closely related to tumor occurrence and development." (PMID 30235236, 2018). "Thus, TFDP3 is involved in the production of tumor cell resistance and, when siRNA inhibits TFDP3 expression, it can reduce cell autophagy so then improve the sensitivity of tumor cells to chemotherapy drugs." (PMID 30235236, 2018). "In the previous study, our research group had found that TFDP3 is related to the apoptosis and drug resistance of tumor cells, and its expression level may be related to the invasion ability of tumor cell lines." (PMID 28797103, 2017). "In this case, TFDP3 could be a potential target for tumor therapies." (PMID 34745961, 2021). "Therefore, these TFDP3-siRNAs can affect the development of tumor cells by interfering cell cycle, which also provides the basis for the study of TFDP3-siRNAs in the treatment of TFDP3-positive tumors to extend the survival time of patients and improve the quality of life of patients." (PMID 28797103, 2017). "To sum up, we speculate that MMP8, MMP11, TFDP3, F2, and CNTN1 can promote the progression of GAC while MYB could be a tumor suppressor in GAC." (PMID 32309437, 2020). "TFDP3 is a novel negative regulator of E2F that can enhance both the DNA binding and transcriptional activity of E2F through the formation of heterodimers; it also potentially plays an important role in the process of tumor development independent of pRb." (PMID 32587798, 2020).
TFDP3 also shares sentences with these, for which no sentence is quoted: diabetes (3 papers); melanoma (3); autoimmune disease (2); infection (2); ovarian carcinoma (2); adenocarcinoma (1); Allergy (1); Autoimmunity (1); benign breast diseases (1); Fibroadenoma (1); hypertrophic cardiomyopathy (1); invasive ductal carcinoma (1); invasive lobular carcinoma (1); malnutrition (1); mucinous carcinoma (1); multiple sclerosis (1); rheumatoid arthritis (1); type-2 diabetes (1); viral infection (1).